ENSG00000206649
Synonyms: LOC124900264
Gene: Small nucleolar RNA gene on chromosome 8 (80,316,939 to 80,317,069, reverse strand). Ensembl gene ENSG00000206649.
Gene Ontology:
Biological process: RNA processing
Cellular component: nucleolus
Homologues: Paralogues in human: SNORA20 (91% identical), SNORA20B (87% identical).